LGALS3BP (galectin 3 binding protein)
Diseases named in the same sentence as LGALS3BP in open-access papers (continued):
Sharing a sentence is not in itself a finding about the gene and the disease.
cancer (continued). "The transcript levels of Galectin-3 (LGALS3) and Galectin-3 binding protein (LGALS3BP), important regulators of innate immune responses often found upregulated in various cancer types 56, were significantly decreased in MLL-r cells." (PMID 34646384, 2021). "Galectin 3-binding protein (LGALS3BP, also known as 90K) is a multifunctional glycoprotein involved in immunity and cancer." (PMID 33824294, 2021). "The galectin 3 binding protein (LGALS3BP, also known as 90K) is a ubiquitous multifunctional secreted glycoprotein originally identified in cancer progression." (PMID 31404116, 2019). "The recent study indicated that LGALS3BP, MUC16, SCGN and SLC39A6 had abnormal expression in various cancer." (PMID 22438889, 2012). "Lectin-galactoside binding soluble 3-binding protein (LGALS3BP, also called Gal-3BP, 90 K, Mac2BP) is a secreted multifunctional glycoprotein found in human influenza virus, serving as a new ligand for Gal-3 that drives cancer progression and dissemination." (PMID 40134029, 2025). "We fitted expression of LGALS3 and LGALS3BP against EMT score and arrayed by tumor immune phenotype to find that LGALS3 expression increases alongside the cancer specific EMT signature expression in every tumor immune phenotype and every delineated EMT phase (i.e., EPI, pEMT, and MES)." (PMID 38086828, 2023). "In conclusion, nanoparticle-mediated delivery of LGALS3BP could potentially improve TNBC treatment, suppressing cancer progression and metastasis." (PMID 37041137, 2023). "LGALS3BP is a glycosylated protein overexpressed in a variety of human malignancies including GBM, being one of the most abundant surface components of cancer‐derived EVs." (PMID 37195369, 2023). "Both LGALS3 and LGALS3BP appear to have higher expression in mesenchymal cancer cells, regardless of the tumor immune phenotype." (PMID 38086828, 2023). "Galectin-3 binding protein (LG3BP) is a heavily glycosylated 90 kDa protein that is expressed in bodily secretions produced mostly by epithelial cells in glands, such as breast and tear ducts, as well as cancer cells." (PMID 35471994, 2022). "Among them, galectin-3-binding protein and ALDH1A1 were found preferentially elevated in TNBC, whereas CK19, transferrin, transketolase, and thymosin β4 and β10 were elevated in HER2-positive cancers." (PMID 22110952, 2011). "Therefore, the LGALS3BP-delivery system may provide effective therapy for TNBC and potentially for other cancer types regulated via aberrant TAK1 activation." (PMID 37041137, 2023). "LGALS3BP reportedly has both negative and positive influences on various cancer prognoses." (PMID 33824294, 2021). "Furthermore, intracellular LGALS3BP has a role in the prevention and treatment of inflammatory diseases by suppressing TAK1-dependent NF-κB activation and regulates centriole biogenesis and centrosome hypertrophy in cancer cells." (PMID 34565385, 2021). "Authors proposed that the antitumor effects of KITENIN knockdown observed in CRC cancer cells might be derived from the generation of tumor-specific immune response through increment of LGALS3BP secretion from non-immune tumour cells." (PMID 34565385, 2021). "Whereas the bio-physiological activity of LGALS3BP is not yet well defined, accumulating evidence has shown that the protein may be involved in cancer growth and progression." (PMID 26219351, 2015). "Importantly, LGALS3BP was demonstrated to bind one or more integrins depending on their availability within a particular cell type, and this unique integrin expression profile could also explain why LGALS3BP is capable of providing adhesion to some but not all cancer cell types." (PMID 34565385, 2021).
tumor (88 papers, 1993 to 2025). "Recently, numerous studies have demonstrated a significant association of LGALS3BP with tumor progression and spread, and an increasing number of studies support the drivers of different processes by which LGALS3BP leads to cellular transformation." (PMID 38393692, 2024). "The diverse pro-tumor mechanisms in which LGALS3BP plays a role are associated with its multi-domain structure and its interactions with various ligands, encompassing adhesion, migration, angiogenesis, motility, and the immune response." (PMID 39434140, 2024). "From this study, they found that high expression of LGALS3BP (lectin galactoside-binding soluble 3 binding protein) in EwS tumor cells is associated with a lower risk to develop metastasis and thus better event-free survival." (PMID 36230825, 2022). "Although Lgals3 and Lgals3bp have been principally linked to tumor aggressiveness and metastasis, previous findings have suggested Lgals3 role in macrophage recruitment." (PMID 33257747, 2020). "Among the top upmodulated genes was the gene encoding galectin 3 binding protein (LGALS3BP), a matricellular protein with a role in tumor progression that has been shown to inhibit EWS proliferation, invasion, and metastasis." (PMID 31209202, 2019). "LGALS3BP, also named as tumor-associated antigen 90K or Mac-2 BP, promotes intergrin-mediated cell adhesion and stimulates host defense against viruses and tumor cells." (PMID 22438889, 2012). "However, some researchers also showed that LGALS3BP acted as a tumor-associated immunomodulatory ligand for Siglec9." (PMID 37106774, 2023). "This association between LGALS3BP and prognosis was confirmed both at mRNA and protein level in tumor tissues but not in serum level, suggesting a role for LGALS3BP in proximity of local tumor microenvironment." (PMID 34565385, 2021). "In addition, we show that high LGALS3BP expression in the tumor tissue is associated with a longer disease-free and overall survival in CRC patients." (PMID 26219351, 2015). "Finally, in a series of 196 CRC patients, LGALS3BP expression in tumor tissue associated with clinical outcome." (PMID 26219351, 2015). "Notably, significantly elevated expression of LGALS3BP in the serum or tumor tissue has been found to be associated with poor clinical outcome in patients with breast carcinoma, hepatocellular carcinoma, pleural mesothelioma, pancreatic carcinoma, non-small cell lung carcinoma and neuroblastoma." (PMID 26219351, 2015). "Given the pro-tumor effects of LGALs3bp, our results showing that LGALs3bp is found in EVs from pro-inflammatory and anti-tumor macrophages suggest possible anti-tumor abilities." (PMID 41279039, 2025). "LGALs3bp is a glycoprotein that has both intracellular and extracellular actions, including increasing angiogenesis, enhancing tumor invasion, and repressing fibrocyte differentiation." (PMID 41279039, 2025). "Their findings suggest that tumor cells increase the release of EVs expressing LGALS3BP, making galectin-3 a promising biomarker for diagnosis and disease monitoring." (PMID 40427551, 2025). "Past studies have shown LGALs3bp to be enriched in the tumor microenvironment, and that its major source was tumor cells." (PMID 41279039, 2025). "The results showed that the transcriptome level of LGALS3BP in the normal group was lower than that in the tumor group." (PMID 38393692, 2024). "The PCR results showed that the expression of LGALS3BP in the normal cell line was lower than that in the tumor cell lines." (PMID 38393692, 2024). "LGALS3BP is significantly upregulated in OSCC tumor tissues, and the PI3K/AKT pathway is regulated by LGALS3BP and affects OSCC proliferation and migration." (PMID 38393692, 2024). "CA9, CYFIP2, and LGALS3BP levels were found to significantly increase as tumour grade increased (p < 0.05)." (PMID 38473425, 2024). "We used a cRGD-liposome (hereafter, cRGD-lipo) for encapsulation and in vivo tumor delivery of LGALS3BP." (PMID 37041137, 2023).
tumor (continued). "We also identified that lgals3bp galectin-3-binding protein, which is regarded as an important clinical tumor biomarker, was downregulated in DMPA users." (PMID 36604469, 2023). "According to IHC data on tumour tissues, we found that LGALS3BP is highly expressed at both mRNA, intracellular and secreted protein levels in all patient‐derived GBM cell lines tested." (PMID 37195369, 2023). "LG3BP (Galectin-3-binding protein) can promote integrin-mediated cell adhesion and it plays an important role in mediated tumor cell survival during the metastatic process." (PMID 36743215, 2023). "Mice overexpressing LGALS3BP showed decreased primary tumor weight, spleen weight, and TNBC metastasis from the primary tumor to the lung." (PMID 37041137, 2023). "By contrast, LGALS3BP increases most in earlier, epithelial phases in all tumor immune phenotypes, and then plateaus, suggesting it is more important in earlier phases of the EM program." (PMID 38086828, 2023). "LGALS3BP is a tumor-secreted antigen and a ligand of the lactose-specific S-type lectin, galactin-3." (PMID 36230825, 2022). "90K, also known as galectin 3 binding protein, LGALS3BP, Mac-2-binding protein, has recently been identified as a tumor-associated antigen and a promising immunotherapy target." (PMID 33686953, 2021). "In this study, they performed methylation-based screening and genome-wide gene expression profiling in combination with a prediction database analysis in 18 OSCC cell lines, and identified a novel tumor-suppressive microRNA miR-596 directly targeting LGALS3BP." (PMID 34565385, 2021). "LGALS3BP expression rate positively correlates with tumor differentiation grade and with recurrence disease during chemotherapy." (PMID 34565385, 2021). "As in depth described up to here, an impressive body of results from the past two decades have been accumulated demonstrating LGALS3BP as an indisputable player in tumor progression and development of metastasis." (PMID 34565385, 2021). "Another multivalent Siglec ligand that has been found on tumor cells or secreted in the TME is LGALS3BP (Mac-2 binding protein)." (PMID 34966391, 2021). "The same study demonstrated that both LGALS3 and LGALS3BP were significantly increased in more aggressive HCC tumours." (PMID 34794390, 2021). "LGALS3BP was found expressed in 43% of stage I/II tumours and 62% of stage III/ IV tumours and positively associated with tumour recurrence." (PMID 34565385, 2021). "The high antitumor activity observed it is thought to occur because of the vast accumulation of LGALS3BP in the tumor allowing accumulation of the therapeutic ADC at the site of the disease." (PMID 34565385, 2021). "Galectin-3 binding protein (Gal-3BP) is a multifunctional, secreted glycoprotein mainly involved in the inflammatory response and tumor transformation and progression." (PMID 32602849, 2020). "Previously, LGALS3BP was reported to be one of the most abundant protein of tumor released exosomes/EVs, where it localizes at the surfaceoma." (PMID 33076448, 2020). "We found that LGALS3BP is overexpressed at a 3.50× greater level in EAC tumor cells compared to normal esophageal cells (P < 0.0001)." (PMID 29868478, 2018). "We demonstrated that high LGALS3BP expression in primary tumor tissue correlated with a better disease-free and overall survival outcome, whereas low LGALS3BP expression correlated with a poorer survival outcome." (PMID 26219351, 2015). "LGALS3BP is a large oligomeric, highly glycosylated protein composed of ≈90 kDa subunits that was originally identified as a tumor-secreted antigen and as a ligand of the lactose-specific S-type lectin, galectin-3 (formerly Mac-2)." (PMID 26219351, 2015). "Galectin-3-binding protein (LGALS3BP) – belongs to a protein family with high affinity for beta-galactoside and it is expressed in many tumor cells being associated to carcinogenesis." (PMID 21858171, 2011).
tumor (continued). "LGALS3BP and CSNK2A2 are associated with the NF-κB pathway, which is crucial in tumor progression." (PMID 39941055, 2025). "Notably, the ability of ST6GAL1 to promote tumor cell proliferation, migration, and colony formation was significantly impaired following LGALS3BP knockdown in SW48-OE cells." (PMID 39937175, 2025). "LGALS3BP expression was significantly higher in tumor tissues compared to normal tissues." (PMID 39937175, 2025). "We first assessed LGALS3BP protein levels in tumor tissues and paired normal tissues using WB." (PMID 39937175, 2025). "Moreover, ST6GAL1 overexpression increased the migration of SW48 cells, further highlighting the role of LGALS3BP sialylation in regulating tumor cell migration." (PMID 39937175, 2025). "Therefore, we compared LGALS3BP mRNA levels in tumor and normal tissues to determine the LGALS3BP expression status." (PMID 38393692, 2024). "Accumulating evidence suggests that LGALS3BP plays a key role in tumor progression and metastasis." (PMID 38393692, 2024). "To test whether LGALS3BP promoted tumor proliferation in ccRCC, we synthesized LGALS3BP-siRNA and transfected 769-P cells." (PMID 38393692, 2024). "Additionally, LGALS3BP, as a heavily glycosylated secreted molecule, was upregulated during tumor progression and bound to human Siglec-9 and other immune-modulatory Siglecs." (PMID 38888513, 2024). "Importantly, we demonstrated that LGALS3BP level detected in EVs isolated in serum of mice harbouring human GBM xenograft significantly correlated with tumour burden." (PMID 37195369, 2023). "In vivo analysis confirmed the suppressive function of LGALS3BP in TNBC tumor progression." (PMID 37041137, 2023). "LGALS3BP inhibited in vivo tumor growth in the orthotopic 4T-1 mouse model." (PMID 37041137, 2023). "Furthermore, to evaluate LGALS3BP expression level in the tumour tissues, we performed the immunohistochemical (IHC) staining of 53 GBM and matched peritumoral samples." (PMID 37195369, 2023). "The EV levels of LGALS3BP are thought to correlate with tumor grade and increased tumor burden." (PMID 38074665, 2023). "In the recent past, a prominent role for LGALS3BP in tumor progression and spreading has been elucidated, and a growing body of evidence is accumulating supporting the notion that this multifunction hyperglycosylated protein is a drive force in different processes leading to cell transformation." (PMID 34565385, 2021). "Therefore, LGALS3BP and galectin-3 were proposed as new modulators of fibrosis in the tumor microenvironment." (PMID 34565385, 2021). "A different line of research proposed LGALS3BP as a tumor suppressor in CRC." (PMID 34565385, 2021). "LGALS3 and LGALS3BP are thus candidate proteins for identifying HCC tumours with increased likelihood for recurrence post-LT, which might represent potential therapeutic targets to diminish HCC recurrence post-LT." (PMID 34794390, 2021). "Importantly, in tumor samples, the expression levels of LGALS3BP showed a direct correlation with those of TGF-β1 (R = 0.34, p < 0.001), USF1 (R = 0.30, p < 0.001), and USF2 (R = 0.37, p < 0.001)." (PMID 33888686, 2021). "The ratios of tumor-infiltrated and splenic MDSCs were significantly increased in Lgals3bp−/− mice." (PMID 33824294, 2021). "Tumor burden was also significantly increased in Lgals3bp−/− mice than that in WT mice." (PMID 33824294, 2021). "Following this unbiased and hypothesis-driven combined approach, we identified S100A8, S100A9, and LGALS3BP as proteins overexpressed in the tumor-initiating cell populations." (PMID 32503348, 2020). "LGALS3BP is a highly glycosylated protein involved in tumor growth and progression." (PMID 33076448, 2020). "LGALS3BP is a glycoprotein that promotes integrin-mediated cell adhesion and may stimulate host defense against viruses and tumor cells." (PMID 29541381, 2018). "Moreover, intra-tumor delivery of LGALS3BP reduced tumor growth of xenografts originating from LGALS3BP-silenced HCT-116 cells." (PMID 26219351, 2015).
tumor (continued). "The role of LGALS3BP as a suppressor of tumor growth was further substantiated by the finding that a significant tumor regression could be achieved with LGALS3BP injected directly into xenografts originating from LGALS3BP-silenced HCTI16 cells." (PMID 26219351, 2015). "Moreover, urinary and serum levels of LGALS3BP were significantly higher in patients compared to healthy individuals, with a strong correlation observed between elevated urinary protein levels and tumor grade." (PMID 41046347, 2025). "The presence of LGALs3bp in EVs from pro-inflammatory and anti-tumor macrophages and its binding partners in EVs from anti-inflammatory macrophages may imply some level of crosstalk between different types of macrophages, although more studies should be done to confirm this pattern." (PMID 41279039, 2025). "Therefore, we speculate that LGALS3BP may have an impact on tumor immunity and may be a target for ccRCC immunity therapy." (PMID 38393692, 2024). "SHOC2 can also promote the expression of LGALS3BP (lectin galactoside-binding soluble 3 binding protein) and so on to control the effect of ERK1/2 pathway on cell movement and adhesion, and the high expression of such proteins in blood and tumor tissues was associated with poor prognosis." (PMID 37166421, 2023). "Therefore, we hypothesized that the delivery of LGALS3BP to the TNBC tumor suppresses TAK1 activity, inhibiting TNBC metastasis." (PMID 37041137, 2023). "So they hypothesized that the implication of LGALS3BP N-glycosylation in pancreatic tumorigenesis was possibly through intensifying the specific interplay between LGALS3BP and galectins to mediate cell−cell and cell-extracellular matrix interaction, angiogenesis, and apoptosis of tumor cells." (PMID 34565385, 2021). "Moreover, therapeutic studies using a rabbit tumor model should be performed to predict whether the serum level of LGALS3BP may affect the efficacy of this ADC due to a potential sink effect." (PMID 33076448, 2020). "The downregulation of cell adhesion proteins (ITGB1, LGALS3, LGALS3BP, SDCBP, PODXL, CDCP1) further suggests a potential impact on tumor cell attachment, migration, and invasion, contributing to the anti-metastatic effects of TSA." (PMID 40429900, 2025). "Of note, LGALS3BP produced by tumor cells treated with a mannosidase I inhibitor, Kifunensine, exhibited increased reactivity to a therapeutic antibody (denoted as "1959"), suggesting that glycosylation of LGALS3BP may influence antibody recognition and protein function." (PMID 41046347, 2025). "Ligand-targeted ADCs are a unique subclass of ADCs directed against cell surface-tethered ligands enriched on tumor cells, such as inhibitory Notch ligand delta-like ligand 3 (DLL3) and Siglec-9 ligand galectin 3 binding protein (LGALS3BP)." (PMID 39065587, 2024). "Nanoparticle-mediated delivery of LGALS3BP exhibited anti-metastatic and antitumor effects, reducing TAK1 phosphorylation and MMP9 expression in TNBC primary tumor tissues." (PMID 37041137, 2023). "These candidate markers (CLDN4, EPCAM, CD151, LGALS3BP, HIST2H2BE, and HIST2H2BF) effectively isolated tumor-derived EVs in clinical samples." (PMID 34948417, 2021). "In silico pathway analysis followed by candidate-based RNA interference mediated loss-of-function analysis revealed a critical role of S100A8, S100A9, and LGALS3BP as molecular determinants of TIC proliferation, migration, and in vivo tumor growth." (PMID 32503348, 2020). "Notably, among the upregulated Exo-prots, we identified proteins that positively regulate tumor development and progression, such as neural cell adhesion molecule (NCAM), nucleolin (NCL) and galectin-3-binding protein (LGALS3BP)." (PMID 37947594, 2023). "Finally, an ADC targeting LGALS3BP, named 1959‐sss/DM4, specifically accumulates in tumour tissue, producing a potent and dose‐dependent antitumor activity." (PMID 37195369, 2023).